CFAP206 (cilia and flagella associated protein 206)
Description:
Essential for sperm motility and is involved in the regulation of the beating frequency of motile cilia on the epithelial cells of the respiratory tract (By similarity). Required for the establishment of radial spokes in sperm flagella.
Synonyms: C6orf165; FLJ25974; dJ382I10.1; SPGF102
Tractability: PROTAC: ubiquitination databases record sites on it.
Gene: Protein-coding gene on chromosome 6 (87,407,972 to 87,464,645, forward strand). Ensembl gene ENSG00000272514.
Subcellular location: Cytoplasm, cytoskeleton, cilium axoneme; Cytoplasm, cytoskeleton, cilium basal body
Gene Ontology:
Molecular function: protein binding
Biological process: sperm axoneme assembly; axoneme assembly; cilium movement; flagellated sperm motility; regulation of cilium beat frequency; regulation of flagellated sperm motility
Cellular component: 9+2 motile cilium; A axonemal microtubule; axoneme; ciliary basal body; cilium; motile cilium; radial spoke; sperm flagellum
Genetic constraint (gnomAD): Loss-of-function variants: 36 observed, 47.93 expected, observed/expected ratio (o/e) 0.75, 90% interval 0.57 to 0.99. The upper end of that interval is the gene's LOEUF score, 0.99, which puts it in group 4 of 6, group 1 being the genes least tolerant of losing a copy. Missense variants: 513 observed, 612.24 expected, observed/expected ratio (o/e) 0.84, 90% interval 0.78 to 0.9. Synonymous variants: 199 observed, 212.24 expected, observed/expected ratio (o/e) 0.94, 90% interval 0.83 to 1.05.
Homologues: Orthologues: chimpanzee CFAP206 (99% identical), macaque CFAP206 (99% identical), pig CFAP206 (84% identical), guinea pig CFAP206 (81% identical), rat Cfap206 (81% identical), mouse Cfap206 (80% identical), rabbit CFAP206 (75% identical), tropical clawed frog cfap206 (64% identical), dog CFAP206 (54% identical), zebrafish cfap206 (48% identical), Drosophila melanogaster CG13436 (18% identical).
Diseases named in the same sentence as CFAP206 in open-access papers:
CFAP206 is named in the same sentence as 4 diseases in open-access papers, as found by Europe PMC text mining. Sharing a sentence is not in itself a finding about the gene and the disease. The quoted sentences say what the papers report.
Infertility (1 paper, 2024). "Therefore, CFAP206 may play a key role in the determination of multiple phenotypes of response to AMDV such as infertility of adults and pneumonia in kits." (PMID 38200094, 2024).
male infertility (1 paper, 2024). The inability of the male to effect fertilization of an ovum after a specified period of unprotected intercourse. "Recent studies showed impaired CFAP206 might result in male infertility and dysfunction of mucociliary clearance of the airways." (PMID 38200094, 2024).
CFAP206 also shares sentences with these, for which no sentence is quoted: pneumonia (1 paper); tumor (1).